COMP (cartilage oligomeric matrix protein)
Diseases named in the same sentence as COMP in open-access papers (continued):
Sharing a sentence is not in itself a finding about the gene and the disease.
lung carcinoma (4 papers, 2020 to 2022). "Similar to the present data, a meta-analysis in lung adenocarcinoma patients also exhibited a strong relationship between ITGB8 and COMP, contributing to the regulation of lung cancer metastasis and poor treatment outcomes." (PMID 35056061, 2021).
lymph node metastases (4 papers, 2018 to 2024). "Lymph node metastases (LNM) with COMP expression were associated with reduced survival." (PMID 34884987, 2021). "We have found that high cartilage oligomeric matrix protein (COMP) mRNA expression in PTC tissues, and that COMP expression was positively correlated with tumor size and lymph node metastasis 10, suggesting that COMP was involved in the occurrence of PTC." (PMID 33613749, 2021). "The expression level of COMP was significantly and positively related to the tumor sizes of PTC patients and the risk of lymph node metastasis." (PMID 33613749, 2021). "We found that COMP was positively correlated with tumour size, lymph node metastasis, and TNM stage." (PMID 29967488, 2018). "In addition, the expression levels of COL3A1, COMP, and ZAP70 were positively related to the risk of lymph node metastasis." (PMID 29967488, 2018). "Given the positive correlation between COMP upregulation and PTC lymph node metastasis 10, we further evaluated how COMP affected the migration and invasion of PTC cells." (PMID 33613749, 2021).
psoriasis (4 papers, 2015 to 2025). An autoimmune condition characterized by red, well-delineated plaques with silvery scales that are usually on the extensor surfaces and scalp. "Estimated odds of having psoriasis increased by about 3% if COMP increased by about 1 ng/mL, by about 25.8% if IL-20 increased by about 1 pg/mL, and almost twice if OPG increased by about 1 pmol/L." (PMID 26146462, 2015). "All selected hub genes present a similar expression pattern among AA, psoriasis, and AGA data sets, except four genes, including CHAC1, COMP, and HOXC13." (PMID 35983595, 2022). "Results of the conducted study suggest that COMP, OPG, IL-20, and OPG/sRANKL ratio may appear useful biomarkers of bone and cartilage involvement in psoriasis." (PMID 26146462, 2015).
psoriatic arthritis (4 papers, 2012 to 2023). Joint inflammation associated with psoriasis. "The results of this study show that COMP and PG-AG may be sensitive markers differentiating patients with osteoarthiritis from psoriatic arthritis." (PMID 33396347, 2020).
systemic lupus erythematosus (4 papers, 2012 to 2025). An autoimmune multi-organ disease typically associated with vasculopathy and autoantibody production. "Elevations of COMP have also been reported in vascular atherosclerosis, systemic lupus erythematosus (SLE), renal fibrosis, degenerating acinar cells of chronic pancreatitis, and liver cirrhosis." (PMID 24376648, 2013). "COMP-C3b levels were significantly elevated in patients with RA as well as in systemic lupus erythematosus (SLE), compared with healthy controls." (PMID 22264230, 2012).
Autoimmunity (3 papers, 2012 to 2020). The occurrence of an immune reaction against the organism's own cells or tissues. "In this study, we provide evidence to show that mAbs to defined epitopes on COMP are indeed pathogenic, thereby emphasizing a link to COMP-mediated autoimmunity." (PMID 22906101, 2012). "The genetic deletion (e.g., PD-1, analogous to VISTA) in mice results in autoimmunity; VISTA fusion protein (VISTA.COMP) reduced acute inflammatory hepatitis in an experimental model." (PMID 32929361, 2020).
cartilage disease (3 papers, 2022 to 2024). Softening and degeneration of the CARTILAGE. "For instance, ER disruption by the mutation in HCs could affect folding of type II, IX, X, and XI collagen; martrilin-3; cartilage oligomeric matrix protein (COMP); and other matrix proteins known to cause cell stress in chondrocytes in various cartilage disorders." (PMID 34990412, 2022).
dilated cardiomyopathy (3 papers, 2015 to 2024). Cardiomyopathy which is characterized by dilation and contractile dysfunction of the left and right ventricles. "COMP deficiency leads to dilated cardiomyopathy by reducing integrin β1 expression and signaling." (PMID 38580957, 2024).
Duchenne muscular dystrophy (3 papers, 2014 to 2025). Duchenne muscular dystrophy (DMD) is a neuromuscular disease characterized by rapidly progressive muscle weakness and wasting due to degeneration of skeletal, smooth and cardiac muscle. "COMP is also a biomarker of tissue fibrosis in Duchenne muscular dystrophy and participates in fibrotic changes in hepatocellular carcinoma." (PMID 41009743, 2025).
dwarfism (3 papers, 2013 to 2022). "However, such comparisons demonstrate that based on bone growth, the ColIITgcog mouse dwarfism is milder than that seen in the Matn3 p.V194D and ColIITgrwd mice but apparently greater than that seen in the COMP p.T583M mouse at 3 weeks of age." (PMID 25693198, 2015).
Epiphyseal dysplasia (3 papers, 2014 to 2023). "Indeed, mutations in the genes encoding COMP and matrilin-3 result in multiple epiphyseal dysplasias." (PMID 24886698, 2014). "Furthermore, our findings suggest that p.G11A of HOXD13 may cause severe short stature without limb deformity, and that the p.D401N variant of the COMP gene may cause multiple epiphyseal dysplasia." (PMID 30541462, 2018).
liver cancer (3 papers, 2024 to 2025). An epithelial or non-epithelial malignant neoplasm that arises from the liver. "It is found that liver cancer-associated fibroblasts secrete COMP to promote proliferation, invasion, migration and EMT in liver cancer cells." (PMID 38374893, 2024). "It is indicated that the association between ITGAV, SPP1, COL4A2, COMP, and immune cells may be involved in the progression of liver cancer." (PMID 38374893, 2024). "In addition, ROC analysis showed that ITGAV, SPP1, COL4A2, and COMP had a potential diagnostic value for liver cancer patients." (PMID 38374893, 2024). "Based on 4 genes (COMP, SPP1, COL4A2, and ITGAV) in the pathway of integrin cell surface interactions, a risk score model for prognosis of liver cancer was constructed." (PMID 38374893, 2024). "The risk score model constructed by genes (COMP, SPP1, COL4A2, and ITGAV) in the pathway of integrin cell surface interactions may be used to predict survival in liver cancer patients." (PMID 38374893, 2024). "In pathway of integrin cell surface interactions, COL4A2, COMP, ITGAV, and SPP1 were used to perform LASSO Cox regression analysis to construct the prediction model of the overall survival rate of liver cancer patients in the TCGA database." (PMID 38374893, 2024). "The mRNA expression levels of COL4A2, COMP, ITGAV, and SPP1 were significantly increased in liver cancer tissues." (PMID 38374893, 2024). "The RT-qPCR experiment was applied to further analyze the expression patterns of 3 key genes (COMP, ITGAV, and SPP1) in liver cancer patients who relapsed after 3 and 6 months." (PMID 38374893, 2024). "Thus, it can be seen that COMP, SPP1, and COL4A2 play important roles in the development of liver cancer." (PMID 38374893, 2024).
periampullary adenocarcinoma (3 papers, 2023 to 2024). An adenocarcinoma that arises from the periampullary region. "A recent study revealed that COMP is highly expressed in pancreatobiliary type periampullary adenocarcinoma, which was associated with the exclusion of CD8+ T-cells from the cancer cell compartment." (PMID 38563861, 2024). "Cartilage Oligomeric Matrix Protein (COMP) is an oncogenic protein that has been associated with a decrease in infiltrating T-cells in periampullary adenocarcinoma." (PMID 37207219, 2023). "Investigating the expression of COMP in patients with periampullary adenocarcinoma, we discovered that T-cells were excluded from the cancer cell compartment in tumors with high levels of COMP expression." (PMID 37207219, 2023). "Recently we revealed that periampullary adenocarcinomas expressing high levels of COMP had denser collagenous matrix correlating with the immune exclusion of T-cells from the cancer cells compartment of the tumors." (PMID 37207219, 2023).
reactive arthritis (3 papers, 2012 to 2025). Reactive arthritis (ReA) is an autoimmune disorder belonging to the group of seronegative spondyloarthropathies and is characterized by the classic triad of arthritis, urethritis and conjunctivitis. "Studies in OA, RA and reactive arthritis have shown that COMP is degraded and released into serum and/or urine in the early pathogenic stages, with serum COMP (sCOMP) levels distinguishing between OA and healthy individuals and reflecting disease severity." (PMID 38528617, 2024).
adenoma (2 papers, 2020 to 2022). A neoplasm arising from the epithelium. "The expression of COMP and TAGLN significantly increased during the colorectal normal-adenoma-adenocarcinoma sequence (all p< 0.05), and patients with high expression of COMP and TAGLN had high clinical staging." (PMID 32754278, 2020).
adhesive capsulitis (2 papers, 2016 to 2025). "The bursitis observed in this case may stem from disturbed joint alignment in MED caused by ligament and tendon laxity resulting from mutations in the COMP gene, which affects the cartilage proteins in these structures." (PMID 40046393, 2025). "In the present study, we quantified the mRNA expression of the TGFβ1, TGFβR1, LOX, PLOD1, PLOD2, COMP, FN1, TNC and TNXB genes in glenohumeral synovium/capsule samples collected from patients with adhesive capsulitis and from controls." (PMID 27438566, 2016).
atrial fibrillation (2 papers, 2021 to 2025). A disorder characterized by an electrocardiographic finding of a supraventricular arrhythmia characterized by the replacement of consistent P waves by rapid oscillations or fibrillatory waves that vary in size, shape and timing and are accompanied by an irregular ventricular response. "COMP knockdown inhibits the activation of the TGF-β pathway, leading to atrial fibrosis and atrial fibrillation." (PMID 41009743, 2025).
bladder cancer (2 papers, 2023). "Our own sequencing data found that the expression level of COMP/DPYSL2 in bladder cancer cases with response to tislelizumab combined with nab-paclitaxel therapy significantly decreased after treatment; however the expression level of TMPRSS4 increased after treatment in non-responsive cases." (PMID 37965307, 2023).
brain cancer (2 papers, 2021 to 2024). A primary or metastatic malignant neoplasm affecting the brain. "COMP (cartilage oligomeric matrix protein) was identified as the most upregulated gene, whereas the most downregulated gene was DMBT1 (deleted in malignant brain tumors 1)." (PMID 33540589, 2021).
brucellosis (2 papers, 2018 to 2020). Brucellosis is a bacterial infection that spreads from animals to people via unpasteurized dairy products or by exposure to contaminated animal products or infected animals. "In this study, the median levels of serum NPT and COMP in brucellosis patients at an early period were elevated, which indicated the changes of the immune system and cartilage among the people diagnosed as brucellosis." (PMID 30180854, 2018). "There were many research on the serum changes of NPT and COMP levels in musculoskeletal diseases; however, these research were rarely found in human brucellosis, which also resulted in osteoarticular changes." (PMID 30180854, 2018). "The serum NPT and COMP levels of brucellosis patients at an early period were increased." (PMID 30180854, 2018). "The serum NPT and COMP levels might be the indicator biomarker for osteoarticular changes of human brucellosis at an early stage." (PMID 30180854, 2018). "COMP could be used as a biomarker of osteoarticular changes in human brucellosis." (PMID 30180854, 2018). "We detected the serum COMP and NPT of patients infected with brucellosis to find the biomarkers for osteoarticular changes in this disease." (PMID 30180854, 2018). "Through this study, we found that brucellosis patients can happened the changes of serum NPT and COMP levels, which might be related with the immune system and cartilage lesions." (PMID 30180854, 2018). "There were changes of serum NPT and COMP levels among human brucellosis with/without different osteoarticular changes at an early period." (PMID 30180854, 2018).
cholangiocarcinoma (2 papers, 2023 to 2024). A carcinoma that arises from the intrahepatic biliary tree (intrahepatic cholangiocarcinoma) or from the junction, or adjacent to the junction, of the right and left hepatic ducts (hilar cholangiocarcinoma). "As determined using immunohistochemistry, poorly differentiated and higher T stage cholangiocarcinoma had greater COMP immunoreactivity than well differentiated and lower T stage cholangiocarcinoma." (PMID 37838792, 2023). "To recognize the potential functions of COMP in IHCC, we downloaded the top two hundred differentially expressed transcripts showing positive connections or negative connections with COMP from the cholangiocarcinoma dataset (TCGA, n = 51)." (PMID 37838792, 2023).
colitis (2 papers, 2018 to 2020). Inflammation of the colon. "We observed that COMP-Ang1-treated mice showed less weight loss, fewer clinical signs of colitis, and longer colons than Ade-DSS-treated mice." (PMID 29610929, 2018). "In this study, we investigated the mechanism underlying the effect of COMP-Ang1 on colitis symptoms and changes in lymphatic vessel density in acute colitis." (PMID 29610929, 2018). "Treatment with COMP-Ang1 reduced the DSS-induced increase in infiltration of ER-HR3-positive macrophages in colitis tissue." (PMID 29610929, 2018). "Surprisingly, systemic delivery of COMP-Ang1 significantly reduced the density of lymphatic vessels in the DSS-induced colitis model." (PMID 29610929, 2018). "The effect of COMP-Ang1 on activated macrophages in colitis was also investigated to determine whether they are involved in the colonic immune response." (PMID 29610929, 2018). "COMP-Ang1 also significantly reduced the density of LYVE-1-positive lymphatic vessels and the disruption of colonic architecture that is normally associated with colitis and repressed the immunoregulatory response." (PMID 29610929, 2018). "We investigated the effects of COMP-Ang1 on an experimental colonic inflammation model." (PMID 29610929, 2018). "Furthermore, COMP-Ang1 may possess a therapeutic range in which it exerts both anti-inflammatory and beneficial effects in colitis." (PMID 29610929, 2018). "In our previous study, we reported that COMP-angiopoietin-1 reduces the expression of VEGF-C and -D mRNA in colitis." (PMID 33138094, 2020). "COMP-Ang1 administration alleviated these symptoms, which indicated that COMP-Ang1 reduced DSS-induced colitis." (PMID 29610929, 2018).
Crohn disease (2 papers, 2017 to 2021). A gastrointestinal disorder characterized by chronic inflammation involving all layers of the intestinal wall, noncaseating granulomas affecting the intestinal wall and regional lymph nodes, and transmural fibrosis. "Further, biomarkers of fibrostenosing Crohn’s disease are unavailable, despite some such as cartilage oligomeric matrix protein, hepatocyte growth factor activator, and lower levels of microRNA-19-3p which are promising." (PMID 34575156, 2021). "In an attempt to non-invasively differentiate predominantly fibrostenotic from inflammatory intestinal injury, this study has highlighted COMP and HGFA among several glycoproteins identified by LC-MS/MS as potential serum biomarkers of fibrosis in Crohn’s disease." (PMID 28114331, 2017).
diabetic retinopathy (2 papers, 2016 to 2020). "Alternatively, adenoviral delivery (AAV2) of a recombinant version of ANG‐1, called COMP‐ANG‐1, demonstrated a protective function of ANG‐1 in models of choroidal neovascularization and diabetic retinopathy." (PMID 27742718, 2016).
disc degeneration (2 papers, 2020 to 2024). "In contrast, the rupture of annulus fibrosus during the later stages of disc degeneration, providing a patent route for releasing higher levels of COMP/ADAMTS7 into blood." (PMID 38528617, 2024). "We first explored the relationship between circulating and tissue COMP levels using a disc degeneration model in rabbits." (PMID 38528617, 2024).
dyslipidemia (2 papers, 2017 to 2019). "To examine whether COMP-Ang1 reversed dyslipidemia in STZ-induced diabetic mice, we measured serum free fatty acid (FFA) and triglyceride levels." (PMID 29212268, 2017).
endometriosis (2 papers, 2021 to 2022). The growth of functional endometrial tissue in anatomic sites outside the uterine body. "Although the cells that secrete COMP are unknown, they reported that COMP could be a potential diagnostic and predictive biomarker of endometriosis." (PMID 36012514, 2022). "This study also reports the first time that the proteins COMP, AGT, TGFBI and ANGP4 have been associated with endometriosis." (PMID 34686725, 2021). "Significantly higher levels of COMP in patients with endometriosis indicate that COMP has a role in pathogenesis of endometriosis and can serve as a potential biomarker or drug target." (PMID 34686725, 2021). "We hypothesize that COMP induces collagen deposition and participates in extracellular matrix remodeling, and might thus contribute to the pathophysiology of intraperitoneal adhesions in endometriosis." (PMID 34686725, 2021). "According to our review of the literature here, COMP, AGT, TGFBI and ANGP4 have not yet been associated with endometriosis, while S100A8, C163A, EGFR and TIMP1 have." (PMID 34686725, 2021). "For three candidate biomarkers, COMP, TGFBI and AGT, with increased levels in the peritoneal fluid no earlier reports in the context of endometriosis were found." (PMID 34686725, 2021).
growth disorders (2 papers, 2018 to 2023). "All these variants were identified in genes already associated with growth disorders: PROKR2 (N = 2), PTPN11 (N = 6), ANKRD11 (N = 1), NPR2 (N = 1), NF1 (N = 1), ACAN (N = 1), GH1 (N = 1), FBN1 (N = 1), COMP (N = 1), IGF1R (N = 1), ARID1A (N = 1), and CASR (N = 1)." (PMID 37605180, 2023).
Hip dysplasia (2 papers, 2014 to 2017). The presence of developmental dysplasia of the hip. "COMP p.Asp469del knock-in mice developed a progressive short-limb dwarfism and hip dysplasia, with disorganized growth plate." (PMID 29262782, 2017). "In comparison between MATN-3 and COMP-MED, the COMP-MED patients were shorter in height, and had more gait abnormality and hip dysplasia, while the MATN3-MED patients had a relatively milder phenotype from an orthopaedic point of view." (PMID 24629099, 2014).
idiopathic scoliosis (2 papers, 2018 to 2019). A scoliosis with no known cause. "The serum level of COMP was lower in children with idiopathic scoliosis and high COMP was modestly correlated with high growth velocity." (PMID 30188931, 2018). "Gerdhem found that COMP was lower expressed in idiopathic scoliosis children." (PMID 30886859, 2019).
infarction (2 papers, 2024 to 2025). A localised pathological necrosis of tissue resulting from obstruction of the blood supply usually by a thrombus, an embolus, or vascular torsion. "In contrast, the downregulation of proteins such as ACTN1, MYL9, CSRP1, COMP, and PI16, which are closely associated with muscle cell development and contractility, suggests a disruption in muscular and structural integrity within the heart in the acute phase post-infarction." (PMID 39513871, 2024).